INS (insulin)
Diseases named in the same sentence as INS in open-access papers (continued):
Sharing a sentence is not in itself a finding about the gene and the disease.
Insulin resistance (continued). "The role of insulin resistance in MASLD among women with PCOS is supported by studies showing that improving insulin sensitivity—through weight loss or pharmacologic agents—ameliorates reproductive, metabolic, and hyperandrogenic symptoms." (PMID 40729034, 2025). "BCAAs are known to modulate insulin secretion and β-cell proliferation, and the disruption of their metabolism has been linked to insulin resistance in T2D." (PMID 40806035, 2025). "Among the four mammalian IRS proteins (IRS-1, IRS-2, IRS-3, IRS-4), IRS-1 and IRS-2 are considered key nodes in the insulin signaling system, and their dysfunction is closely linked to the development of insulin resistance." (PMID 39966707, 2025). "Central obesity – prominently hypertrophic adipocytes - has been linked to the disruption of insulin signaling and insulin resistance, possibly via diet-induced inflammation." (PMID 41403901, 2025). "Cord serum lipid concentrations were associated with insulin resistance and β-cell function in the offspring, and these associations were modulated by maternal treatment during pregnancy (i.e. metformin vs. insulin)." (PMID 40544417, 2025). "The need for improved treatments of IDDM remains unmet due to the potential drawbacks of insulin therapy, including an increased risk of life-threatening hypoglycemia and weight gain, which are associated with insulin resistance and cardiovascular events." (PMID 40429740, 2025). "Insulin resistance is caused by the persistent overexpression of miR-378 because PI3K is a crucial transcriptional regulator of insulin." (PMID 40565979, 2025). "Expression of eiger, the Drosophila TNF-α homolog, in imaginal discs causes systemic insulin restriction and insulin resistance, reducing protein translation and proliferation in peripheral tissues." (PMID 41353199, 2025). "For example, by using age, BMI, autoantibodies and markers of beta cell function and insulin resistance, individuals can be classified into five subtypes that predict insulin requirements and risk of chronic kidney disease (CKD)." (PMID 39155282, 2025). "Among the six mammalian IRS proteins (IRS-1, IRS-2, IRS-3, IRS-4, IRS-5, IRS-6), IRS-1 and IRS-2 are typically considered key nodes in the insulin signaling system, closely associated with the development of insulin resistance." (PMID 39966707, 2025). "Here, the authors identify a role for DNAJA2 in regulating insulin signaling and glucose metabolism, loss of which causes insulin resistance and type 2 diabetes phenotypes." (PMID 41233317, 2025). "Reduced glucose tolerance and insulin sensitivity result in increased glucose levels and increase the risk of insulin resistance and diabetes." (PMID 40292556, 2025). "The improvement occurs in insulin resistance due to good glycemic control, the decrease in insulin levels, and the associated reduction in body weight leading to the decline in hepatic de novo lipogenesis." (PMID 40085410, 2025). "Thyroxine promotes intestinal glucose absorption, accelerates the oxidative utilization of glucose and hepatic glycogenolysis, affects insulin secretion and action, and causes insulin resistance by reducing insulin secretion and peripheral insulin sensitivity." (PMID 40093748, 2025). "Support for a causal role of hyperinsulinemia in the development of insulin resistance is provided by a prospective study in Pima Indians demonstrating that pancreatic hypersecretion of insulin is the first defect that occurs prior to insulin resistance." (PMID 41009753, 2025). "A significant inverse correlation was found between vitamin D levels and 2 h insulin levels (r = −0.28, p =< 0.01), indicating that lower vitamin D status is associated with increased insulin resistance." (PMID 40868057, 2025). "T2DM is a longstanding metabolic condition caused by insulin resistance and insufficient insulin levels in the blood." (PMID 40535952, 2025).
Insulin resistance (continued). "Another study showed that administering purified SeP caused impaired insulin signaling and dysregulated glucose metabolism in hepatocytes, leading to insulin resistance." (PMID 39858445, 2025). "Smoking can interfere with insulin signaling, leading to insulin resistance, and has been linked to metabolic syndrome, which includes hyperlipidemia." (PMID 40218939, 2025). "Additional loci identified in both groups were implicated in lipid metabolism, energy regulation, and insulin signaling, reinforcing the multifactorial nature of insulin resistance." (PMID 40699860, 2025). "Oxidative stress is suggested to cause insulin resistance by inducing pancreatic beta cell dysfunction and affecting insulin secretion or production." (PMID 39859066, 2025). "Insufficient insulin production characterizes type 1 diabetes, necessitating daily insulin administration, while insulin resistance primarily underlies type 2 diabetes." (PMID 40471961, 2025). "Hypertriglyceridemia is often associated with insulin resistance and can further exacerbate metabolic dysfunction through various mechanisms, including increased hepatic glucose production and impaired insulin sensitivity." (PMID 40423035, 2025). "In cord serum the associations between FA classes and offspring insulin resistance were significant mostly in the insulin group." (PMID 40544417, 2025). "Mechanistic investigations revealed that DNAJA2 deficiency impairs insulin signaling and induces insulin resistance in mouse models." (PMID 41233317, 2025). "Age at menarche was also significantly associated with insulin sensitivity indices such as Homeostatic Model Assessment for Insulin Resistance, Single Point Insulin Sensitivity Estimator, and Quantitative Insulin-sensitivity Check Index." (PMID 38912813, 2025). "Insulin resistance, defined as the increasing insensitivity of tissues towards insulin, is well associated with type 2 diabetes, but is also a critical factor in T1D." (PMID 40429969, 2025). "Secreted hormones include leptin, which signals satiety and regulates energy balance; adiponectin, which enhances insulin sensitivity and counters inflammation; and resistin, which is associated with insulin resistance." (PMID 40553147, 2025). "Dysregulation of purine metabolism is linked to insulin resistance, as elevated serum uric acid and related intermediates correlate with impaired insulin secretion." (PMID 41441003, 2025). "Normal pregnancy is associated with maternal insulin resistance, necessitating greater insulin demand, and consequently, the upregulation of β-cell mass." (PMID 40134803, 2025). "Ketosis is associated with insulin resistance, also known as impaired insulin sensitivity, in dairy cows." (PMID 40108709, 2025). "The METS-IR index, a non-insulin-based metabolic score, represents a new marker closely linked to insulin resistance." (PMID 40421238, 2025). "When undergoing strenuous surgical procedures, it is common for patients’ blood sugar to increase due to the hypermetabolic stress response, which causes an increase in the release of insulin and can also induce insulin resistance." (PMID 40519247, 2025). "T2DM is fundamentally caused by insulin resistance, which is characterized by an impaired response of insulin-responsive cells (e.g., myocytes, adipocytes, hepatocytes) to circulating insulin levels, and is the fundamental cause of T2DM." (PMID 39851765, 2025). "Abnormal hepatic insulin action is assumed to be a very important cause of insulin resistance, in which elevated insulin levels are needed to maintain glucose homeostasis in the blood." (PMID 40141412, 2025). "Instruments were 53 insulin resistance, 109 fasting glucose, 48 fasting insulin and 15 2-h post-load glucose genetic variants with variant-outcome effects estimated adjusting for 10 PCs." (PMID 41388643, 2025).
Insulin resistance (continued). "Although insulin treatment is associated with reductions in insulin resistance, this effect is likely downstream of glucose levels: insulin itself has been proposed to promote insulin resistance." (PMID 38895272, 2025). "And the interaction between APOA1 genetic variants and these non-insulin-based insulin resistance surrogates remains largely unexplored." (PMID 41422312, 2025). "Magnesium deficiency has been shown to impair insulin-mediated glucose uptake and promote insulin resistance through increased oxidative stress and inflammation." (PMID 40895688, 2025). "Insulin resistance represents a fundamental hallmark of T2DM characterized by diminished cellular responsiveness to insulin resulting in impaired glucose uptake and elevated blood glucose levels." (PMID 40136413, 2025). "Smoking is recognized as an independent risk factor for insulin resistance, as it impairs insulin signaling in the liver and muscles, disrupts lipid metabolism, and promotes chronic inflammation and oxidative stress." (PMID 41296790, 2025). "On the other hand, type 2 diabetes is characterized by a spectrum ranging from predominant insulin resistance with relative insulin deficiency to a primary defect in insulin secretion combined with insulin resistance." (PMID 40005351, 2025). "GDM is caused by a failure of insulin secretion and/or a relative insulin deficiency to compensate for insulin resistance during pregnancy resulting in a pregnancy related hyperglycaemia." (PMID 40021748, 2025). "Positive associations with fasting glucose, HbA1c, and insulin point to its involvement in insulin resistance and impaired glucose metabolism." (PMID 41357032, 2025). "These conditions result from a combination of insulin resistance and reduced insulin secretion caused by damage to pancreatic β-cells." (PMID 39997354, 2025). "Plasma AAAs that are positively associated with diets high in animal protein can disrupt insulin function and lead to insulin resistance, thereby increasing the risk of MetS." (PMID 41268578, 2025). "In humans with obesity and in diet-induced obese mice, SIRT3 deficiency induces endothelial insulin resistance, increases mitochondrial ROS, and blunts insulin-stimulated vasorelaxation, linking SIRT3 loss to early vascular metabolic dysfunction." (PMID 41465170, 2025). "Supplementation with MTE and MLE inhibited the elevation of LEP and INS caused by a high-fat diet and reduced insulin resistance, leptin resistance, and blood glucose levels." (PMID 40564320, 2025). "The dominant paradigm posits that hyperglycemia caused by insulin resistance amplifies β-cell secretion of insulin, resulting in compensatory hyperinsulinemia." (PMID 40013621, 2025). "In skeletal muscle, it reduces insulin sensitivity, causing hyperglycemia, while in fat tissue, it increases insulin sensitivity, promoting free fatty acids and insulin resistance." (PMID 40772205, 2025). "Genetic mutations in components of the insulin signaling pathway can also contribute to insulin resistance and induce secondary hyperinsulinemia." (PMID 40013621, 2025). "This improvement in insulin signaling is significant because hyperinsulinemia resulting from insulin resistance is known to enhance ovarian androgen synthesis, a process linked to diminished insulin signaling pathway efficiency." (PMID 40776915, 2025). "Aging is associated with a natural decline in insulin sensitivity, which, when combined with pre-existing insulin resistance, accelerates the onset of dyslipidemia and chronic inflammation." (PMID 40280905, 2025). "CMIP (c-Maf-inducing protein) is known to participate in insulin signaling and T-cell activation pathways, and its polymorphisms have been previously associated with insulin resistance and lipid metabolism abnormalities." (PMID 40507058, 2025).
Insulin resistance (continued). "T2DM is a disease outlined by a nonautoimmune heterogeneously progressive loss of adequate islet β cell insulin secretion frequently in the presence of insulin resistance (IR) and metabolic syndrome (MS)." (PMID 40430501, 2025). "The majority of insulin resistance is closely associated with obesity and metabolic syndrome, resulting in impaired insulin signaling pathways." (PMID 40881124, 2025). "Accordingly, healthcare providers can adapt the LCHF-KD to optimize its impact on ER stress and insulin sensitivity by evaluating a subject’s genetic predisposition to insulin resistance and metabolic profile." (PMID 41567335, 2025). "Lowtemperatures can directly suppress insulin secretion, potentially causinghypokalemia, which exacerbates insulin resistance." (PMID 39867189, 2025). "Insulin monotherapy remains the mainstay of treatment of type 1 diabetes, yet is associated with iatrogenic insulin resistance and insulin resistance is indirectly associated with increased CV risk." (PMID 41285865, 2025). "These inconsistencies highlight the urgent need for well-designed longitudinal studies to evaluate causal relationships and distinguish the direct effects of insulin and insulin resistance from other metabolic influences on bone health." (PMID 40564223, 2025). "Oxidative stress can damage the pancreatic β-cells, resulting in decreased insulin secretion and interfere with the normal function of insulin receptors, leading to insulin resistance, and thereby increasing the risk of GDM." (PMID 39997932, 2025). "Changes in the insulin signaling pathway within these tissues lead to insulin resistance, a hallmark of T2DM." (PMID 39996906, 2025). "This persistent low-grade inflammation, termed metabolic inflammation, impairs insulin signaling in peripheral tissues and contributes to systemic insulin resistance, which is a hallmark of obesity and metabolic syndrome." (PMID 41007736, 2025). "We found its positive association with BMI, glycated hemoglobin, leptin, insulin, IL-8 and IL-10 levels supporting a galectin-1 interconnection with glucose control, insulin resistance and inflammation." (PMID 40698658, 2025). "Higher levels of long-chain (C16–C22) ceramides are associated with insulin resistance, whereas very-long-chain (C > 22) ceramides are associated with improved insulin sensitivity." (PMID 40630937, 2025). "The pathogenesis of type 2 diabetes is caused by the interaction of insulin dysfunction and insulin resistance." (PMID 40860658, 2025). "On the contrary, the pathogenesis of type 2 diabetes is the increase in insulin concentration caused by prophase insulin resistance." (PMID 40092731, 2025). "When PTP1B is overexpressed, protein tyrosine kinase (PTK) activity is reduced, causing insulin resistance by preventing insulin and its receptor from interacting." (PMID 40863620, 2025). "It is closely associated with insulin resistance in adipose tissue and participates in the regulation of insulin sensitivity through the MAPK and NF-κB pathways." (PMID 41460830, 2025). "Pathway analyses revealed enrichment in integrin cell surface interactions and insulin signaling pathways, underlining the importance of these biological processes in obesity-related insulin resistance." (PMID 40862085, 2025). "High-fiber diets have been shown to enhance the body’s response to insulin, lowering insulin resistance-a condition often linked to type 2 diabetes and obesity." (PMID 40026940, 2025). "Skeletal muscle, the most efficient target organ for insulin-mediated glucose disposal in the body, is closely associated with insulin resistance." (PMID 40034234, 2025). "In iGDM patients, an adipose tissue–associated insulin resistance seems to be responsible for the reduced insulin sensitivity in peripheral target tissues." (PMID 39384641, 2025). "Overproduction of glucagon, along with insufficient insulin secretion to compensate for insulin resistance, causes high blood glucose values." (PMID 41179869, 2025).
Insulin resistance (continued). "This disease is characterized by marked insulin resistance and strong deficient secretion, a situation that renders persistent insulin deficit and hyperglycemia." (PMID 40559420, 2025). "High autoantibody levels inhibit the INSR (antagonistic role), causing insulin resistance and hyperglycemia, while low levels of these autoantibodies partially agonize insulin-mimetic activity, causing hypoglycemia." (PMID 40565151, 2025). "Neonates born SGA show greater circulating triglycerides and lower HDL concentration compared to their AGA peers, while prepubertal children born SGA show greater circulating insulin concentration, potentially predisposing them to insulin resistance." (PMID 40889096, 2025). "Weight loss reduces insulin resistance, improves pancreatic beta‐cell function and enhances hepatic and skeletal muscle sensitivity to insulin." (PMID 39718468, 2025). "Cross‐sectional analyses in our study showed mixed results: associations of higher serum insulin and insulin resistance markers with a lower cognition across several domains, but a higher hippocampal volume." (PMID 40478656, 2025). "In states of insulin resistance, decreased efficiency of insulin action can be associated with elevated blood glucose and lipid levels, which are closely related to increased inflammation and oxidative stress." (PMID 40529428, 2025). "Elevated urea levels have been linked to an increased likelihood of insulin resistance and reduced insulin production, contributing to excessively high blood glucose levels." (PMID 39997721, 2025). "Women with phenotypes A and B usually also have menstrual dysfunction, increased risk for metabolic syndrome (increased insulin secretion and insulin resistance), dyslipidemia, hepatic steatosis, and a higher incidence of obesity." (PMID 40869469, 2025). "Vitamin D deficiency is associated with increased risk of insulin resistance and type 2 diabetes, as it impairs insulin secretion, reduces insulin sensitivity, and promotes inflammation and oxidative stress, all of which disrupt glucose metabolism." (PMID 40739560, 2025). "Conversely, resistin, an adipokine associated with insulin resistance and type 2 diabetes, can disrupt insulin signaling." (PMID 41378205, 2025). "Our observations in respect of the association of insulin resistance with high insulin level and advanced age appear to support previous studies." (PMID 40273152, 2025). "Elevated circulating free fatty acids, a hallmark of high-fat intake, promote insulin resistance while simultaneously constraining the compensatory capacity of β-cells to maintain adequate insulin secretion." (PMID 41374066, 2025). "Insulin resistance is a hallmark of hyperinsulinaemia, characterised by a diminished response of insulin‐sensitive tissues (such as adipose tissue, skeletal muscle and liver) to insulin stimulation." (PMID 40522008, 2025). "Of note, PTEN signaling negatively regulates of insulin signaling and associated with the development of insulin resistance in T2D." (PMID 40251348, 2025). "Insulin antibody-mediated insulin resistance is a rare autoimmune mechanism that can cause severe hyperglycemia." (PMID 40696585, 2025). "Habitual physical activity is associated with lower insulin resistance, improved insulin sensitivity, and better glycemic control." (PMID 41431696, 2025). "Insulin resistance, often linked to excess body weight, is characterized by a diminished responsiveness of insulin-sensitive tissues to insulin action." (PMID 39656436, 2025). "Previous studies on the GRS have consistently demonstrated that it is strongly associated with decreased insulin secretion, but that it generally shows a weaker or negligible relationship with insulin resistance." (PMID 39902403, 2025). "The findings revealed that higher serum β-carotene concentrations were associated with improved insulin sensitivity two decades later, suggesting a potential long-term protective effect against insulin resistance." (PMID 40563357, 2025).